TIAM1 (TIAM Rac1 associated GEF 1)
Diseases named in the same sentence as TIAM1 in open-access papers (continued):
Sharing a sentence is not in itself a finding about the gene and the disease.
pancreatic cancer (10 papers, 2010 to 2024). "Rac1 and two of its GEFs, Tiam1 and Vav1, have been reported to be overexpressed in more than 70% of pancreatic cancers, and Vav1 overexpression has also been associated with poor prognosis in pancreatic cancer patients." (PMID 25344910, 2014). "As yet, however, the mechanism of Tiam1 in glycolysis reprogramming of pancreatic cancer (PC) remains to be clarified." (PMID 38017477, 2023). "To gain a deeper understanding of the Tiam1 in pancreatic cancer (PC), we analysed the expression of Tiam1 is highly expressed in PC tissues compared to that in adjacent normal pancreatic tissues according to the KM-plotter, GEPIA, and Sangerbox portals." (PMID 38017477, 2023). "Many GEFs such as Vav1 and Tiam1 that are overexpressed in pancreatic cancer are known to promote Rac1 activation." (PMID 28410221, 2017). "In pancreatic cancers, more than 70% of tumors overexpressed the Rac1 GEFs Tiam1 and Vav1." (PMID 28410221, 2017). "Rac1 and two of its GEFs, Tiam1 and Vav1, are overexpressed in more than 70% of pancreatic cancers." (PMID 25344910, 2014). "Since Tiam1 and Rac1 are active in the majority of pancreatic cancer cells, Tiam1 might mediate the activation of Rac1." (PMID 24281169, 2010). "For example, in contrast to skin cancer, where TIAM1 is required for RAS-induced tumor initiation and growth but antagonizes malignant conversion, in pancreatic cancer, TIAM1-RAC1 signaling promotes both proliferation and invasion." (PMID 37748077, 2023).
cervical carcinoma (9 papers, 2012 to 2025). A carcinoma arising from either the exocervical squamous epithelium or the endocervical glandular epithelium. "Moreover, in papillary thyroid cancer, esophageal squamous cell carcinoma, metastatic hepatocellular carcinoma, and cervical cancer, Tiam1 overexpression was implicated with poor prognosis and a low survival rate." (PMID 32322580, 2020). "According to our findings, the CHD6 gene exhibited higher expression than the RIMS1, MORC4, FMO5, TIAM1, and other genes in cervical cancer." (PMID 40847033, 2025). "Rac1 inhibitor NSC23766 inhibited Rac1 activation by Rac-specific GEFs Trio or Tiam1 in ovarian and cervical cancer." (PMID 32443784, 2020). "The study demonstrated high expression of Tiam1 in cervical cancer specimens compared to cervical intraepithelial neoplasia and normal cervical tissues." (PMID 32443784, 2020). "In this study we analyzed the expression of the GTPases Rac1, RhoA, Cdc42, and the Rho-GEFs, Tiam1 and beta-Pix, in cervical pre-malignant lesions and cervical cancer cell lines." (PMID 22443139, 2012). "Additionally, LYPLA1 was found to be highly expressed in malignant cervical cancer tissues, where it was associated with the upregulation of EMT-inducing TIAM1 and GREM1 and a decrease in mesenchymal markers." (PMID 37644433, 2023). "Several studies have identified TIAM1 as an oncogene due to its overexpression or mutation in epithelial cancers with poor prognosis, such as non-small cell lung cancer (NSCLC), stomach, endometrial, colorectal, pancreatic, and cervical cancer." (PMID 32322580, 2020). "Further Tiam1, a known oncogene is dysregulated in NSCLC, endometrial, colorectal, pancreatic, and cervical cancer and is known to activate both Rac-1 and Cdc42." (PMID 37024613, 2023).
breast tumor (8 papers, 2008 to 2024). "The role of Rho GTPases in BC has also been indicated from the report that progression of breast tumors is accompanied by a decrease in expression of the Rho guanine exchange factor TIAM1 and is inversely associated with several established breast tumor markers." (PMID 27902969, 2017). "Research showed ankyrin-Tiam1 interaction plays a pivotal role in regulating Rac1 signaling and cytoskeleton function required for oncogenic signaling and metastatic breast tumor cell progression." (PMID 28245581, 2017). "In this current study, we observed a positive correlation between Tiam1 expression and motility in a panel of breast tumor cell lines." (PMID 20819206, 2010). "This suggests that breast tumor cell lines regulate Golgi reorientation through distinct mechanisms and that Tiam1 can regulate multiple aspects of the motile phenotype." (PMID 20819206, 2010). "Tiam1 protein expression also correlates with migration capacity in breast tumor cell lines, and a close correlation has been observed between increased Tiam1 expression and tumor grade." (PMID 20819206, 2010). "In the current study, we observed a close correlation between Tiam1 expression and motility in a panel of human breast tumor cell lines." (PMID 20819206, 2010). "High levels of expression of all three GEFs studied Trio, Vav1 and TIAM-1 were seen in breast tumours compared with normal background breast tissue." (PMID 18925966, 2008). "High expression levels of Trio, Vav1 and TIAM-1 were seen in breast tumours, especially in those with poor prognosis." (PMID 18925966, 2008). "Moreover, we demonstrated that endogenous Tiam1 is localized to the Golgi apparatus in breast tumor cells, where it regulates at least one Golgi function that is required to support motility." (PMID 20819206, 2010). "Higher grade breast tumours have a higher expression of TIAM-1 which can disturb intercellular adhesiveness by inducing cellular ruffles and may be correlated with the invasive phenotypes of human breast tumours." (PMID 18925966, 2008). "With regard to the specific targets predicted to TNBC, TIAM1 encodes Tiam1 (T-lymphoma invasion and metastasis 1), one of the known guanine nucleotide (GDP/GTP) exchange factors (GEFs) for Rho GTPases (e.g., Rac1) and is expressed in breast tumor cells (e.g., SP-1 cell line)." (PMID 28245581, 2017). "Although several reports have indicated that Tiam1 is overexpressed in breast tumors, the function of Tiam1 in human, tumor-derived breast epithelial cells has not been determined." (PMID 20819206, 2010). "Because Tiam1 supports motility in breast tumor cells without any substantial effect on total cellular Rac-GTP levels, it may represent an attractive target for therapeutic intervention." (PMID 20819206, 2010).
diabetes (8 papers, 2015 to 2021). "This corroborated cell culture data showing that high glucose conditions lead to downregulation of Tiam1, indicating a role both in vitro and in vivo for Tiam1 in diabetes." (PMID 33923452, 2021). "TIAM1-regulated pathways have furthermore been highlighted as targets in autoimmunity, including in islet β cells in health and diabetes." (PMID 32411128, 2020). "Based on the findings, it was concluded that the Tiam1-Rac1-Nox2 signaling pathway plays critical regulatory roles in the onset of spontaneous diabetes in the NOD mouse model." (PMID 33255484, 2020). "Our recent studies have shown that the Tiam1-Rac1-Nox2 signaling module is activated in the initial stages of diabetes to increase intracellular ROS levels leading to mitochondrial damage and accelerated capillary cell apoptosis." (PMID 25967961, 2015). "Other validated target of miR-21 are the fas ligand (Faslg), Pdcd4, and Tiam1 which are also related to diabetes." (PMID 25671565, 2015). "Pharmacological investigations involving Rac1 inhibitors have suggested Tiam1 (NSC23766), Vav2 (Ehop-016) and SoS1 as GEFs involved in sustained activation of Rac1 in the retina in diabetes." (PMID 31277234, 2019). "Studies of Veluthakal and coworkers demonstrated that administration of NSC23766, a known inhibitor of the Tiam1-Rac1-Nox2 signaling pathway, significantly prevented the development of spontaneous diabetes in the non-obese diabetic (NOD) mice." (PMID 33255484, 2020). "The potential protective role that inhibition of Tiam1/Rac1 might play, was further shown through use of an in vivo mouse model of type 1 diabetes (NOD mouse), where intraperitoneal daily injection of NSC23766 significantly prevented the development of spontaneous diabetes." (PMID 33923452, 2021).
melanoma (8 papers, 2013 to 2025). A malignant, usually aggressive tumor composed of atypical, neoplastic melanocytes. "The RhoGEF TIAM is also overexpressed in a cohort of melanoma patients, and it was suggested that TIAM1 regulates RAC to modulate CADHERIN expression during melanoma cell invasion." (PMID 34503171, 2021). "The mutation in BAP1 was captured in the melanoma, as well as mutations in KMT2A (a known cancer driver mutation in melanoma) and TIAM1 (a gene involved in the RAC1 signaling pathway affecting cell shape and migration)." (PMID 35052351, 2021). "TIAM1 is overexpressed in many tumors, including melanoma, and breast, colon, prostate and renal cancers." (PMID 26959888, 2016). "Metastatic melanoma cells overexpressing TIAM1 turned the mesenchymal phenotype into an epithelial-like phenotype, whereas its downregulation enhanced malignant progression." (PMID 27206673, 2016). "Although slight increases in TIAM1 activity were observed in our study, the TIAM1-RAC1 axis cannot be entirely excluded from RAC1P29S activation in cancers, including melanoma." (PMID 41034404, 2025). "Beyond the 4% of melanoma cases with mutant RAC1, it is also worth speculating whether RAC signaling pathways may be activated in melanoma and perhaps other tumor types by different mechanisms, such as alterations in upstream regulatory proteins such as PREX and TIAM1." (PMID 31257073, 2019).
retinoblastoma (7 papers, 2013 to 2021). A malignant tumor that originates in the nuclear layer of the retina. "TIAM1 has also been shown to play roles in neuronal responses to oxygen and glucose deprivation and has been linked to mitochondrial dysfunction in diabetic retinopathy as well as to retinoblastoma." (PMID 32411128, 2020). "The over expression of Tiam1 in breast carcinoma, nasopharyngeal carcinoma, hepatocellular carcinoma, renal cell carcinoma, retinoblastoma, colorectal carcinoma, lung and prostate cancer has been previously reported." (PMID 23950931, 2013). "Ltd for microarray analysis, Dr. Vikas Khetan for providing us with primary retinoblastoma patient samples, John G Collard, Netherlands Cancer Institute for providing the Tiam1 plasmid constructs." (PMID 23950931, 2013). "MicroRNA-target gene-prediction analyses indicate that miRNA-31 and miRNA-200a could significantly target genes that are expressed in primary retinoblastomas, such as TIAM1." (PMID 26379276, 2015). "We observed that PAK2 and MLCK were down-regulated in Tiam1 silenced retinoblastoma Y79 cells." (PMID 23950931, 2013). "The stronger association of TIAM1 than RAC1 with NE gene expression suggests that in NE SCLC increased expression of select GEFs may lead to increased RAC activity independent of total RAC1 levels, consistent with previous findings in retinoblastoma and nodular melanoma." (PMID 34758330, 2021). "Earlier, Tiam1 was shown to be overexpressed in retinoblastoma (RB) and we hypothesized that it was involved in invasiveness of RB." (PMID 23950931, 2013).
skin cancer (7 papers, 2015 to 2023). "The RAC1 GEF TIAM1 is a candidate therapeutic target as TIAM1 is a RAS effector required for oncogenic RAS-induced skin cancer." (PMID 37748077, 2023). "TIAM1-deficient mice are resistant to the development of RAS-induced skin tumors, revealing that TIAM1 is a critical regulator of RAS-induced tumor formation." (PMID 28423360, 2017). "For example, while far fewer skin tumors developed in carcinogen-treated Tiam1 knockout mice, proportionally they more often progressed to malignancy, thus indicating that Tiam1-Rac1 signaling inhibits cancer progression." (PMID 27442895, 2017). "Previously, we showed that Tiam1 knockout mice are resistant to H-Ras-induced skin tumors, implying a requirement for TIAM1 in tumor formation consistent with its roles in cell proliferation and survival." (PMID 25543140, 2015).
intestinal tumors (6 papers, 2008 to 2020). "The interplay of Rac1/Tiam1 and the Wnt pathway is illustrated by the decrease in the number and the size of intestinal tumors following knockout of Tiam1 in APCMin/+ mice." (PMID 32178475, 2020). "Tiam1 upregulation promotes intestinal tumor formation and progression via a feedback loop; aberrant Wnt activation induces Tiam1 transcription, thereby activating Rac1." (PMID 30171257, 2019). "Tiam1 was recently identified as a Wnt-responsive gene that is upregulated in mouse intestinal tumors and human colon adenomas, and promotes intestinal tumour formation and progression." (PMID 18826597, 2008). "Its expression was greatly elevated in mouse intestinal tumors and human colon adenomas, and the cross-talk between TIAM1 and canonical Wnt-signaling pathways could significantly influence intestinal tumor formation and progression." (PMID 26691761, 2015). "However, how TIAM1 influences intestinal tumor initiation and progression remained elusive." (PMID 28416184, 2017).
neuroblastoma (6 papers, 2012 to 2021). Neuroblastoma (NB) is the most common solid, extracranial childhood tumor. "TIAM1-mediated networks are also implicated in neuroblastoma, and therefore, strategies to regulate TIAM1 have been highlighted." (PMID 32411128, 2020). "Our results with 106 primary neuroblastomas reveal that TIAM1 has a higher incidence of variants (11%), and they significantly associate as an independent variable with better outcome, even in the concomitant presence of MYCN amplification or ALK mutation." (PMID 28423360, 2017). "In contrast, another study with 87 neuroblastoma patients, investigators reported 3 mutations in TIAM1 gene, one with concomitant MYCN amplification and poor outcome." (PMID 28423360, 2017). "To further explore the prognostic value of TIAM1 variant in neuroblastoma, we performed a multivariate Cox regression analysis." (PMID 28423360, 2017). "Noteworthy, TIAM1 variant was a clear independent variable to predict prognosis in primary neuroblastoma, further supporting its value as an outcome predictor in the disease." (PMID 28423360, 2017). "These variants in TIAM1 appear to be rare and improve clinical outcome in neuroblastoma presumably by causing a partial or complete dysfunction of the protein." (PMID 28423360, 2017). "To understand the role of the identified variants in neuroblastoma etiology and progression, we assessed the predictive effect of each variant in the signaling domains of TIAM1 protein and the clinical features of each patient." (PMID 28423360, 2017). "One explanation for the higher percentage of TIAM1 variants found in our cohort vs. previous reports is that we focused strictly on primary neuroblastomas and we took into account both low and high risk groups." (PMID 28423360, 2017). "Somatic mutations in ALK have been reported in 7% of neuroblastoma cases, with mutations in TIAM1 reported in 3%." (PMID 24349301, 2013). "More recently, a whole-genome sequence analysis of 87 neuroblastomas showed three mutations in TIAM1 as well as other mutations in regulators of the Rac/Rho pathway, suggesting that defects in neuritogenesis may contribute to neuroblastoma." (PMID 28423360, 2017). "Collectively, TIAM1 variants associated with better outcome in neuroblastoma patients and therefore, suggest that inhibiting TIAM1 in neuroblastoma could be used in conjunction with conventional therapy to improve outcome." (PMID 28423360, 2017). "The detected variants are located within the different domains of TIAM1 that signal to the upstream regulator RAS and downstream effector molecules MYC and RAC, which are all implicated in neuroblastoma etiology and progression." (PMID 28423360, 2017). "Cellular polarity in neuroblastoma cells is controlled by TIAM1-dependent RAC activation mediated by the polarity complex PAR-6-PAR-3." (PMID 28423360, 2017). "In the present study, we screened primary neuroblastomas by next generation sequencing and our results reveal that TIAM1 variants in the domains signaling to MYC, RAS and RAC significantly predict better prognosis in neuroblastoma patients." (PMID 28423360, 2017). "These novel observations implicate TIAM1 as a key signaling molecule in neuroblastoma and as a potential target for therapeutic intervention." (PMID 28423360, 2017). "Nonetheless, the role of TIAM1 in neuroblastoma cells has been mostly focused in neuritogenesis." (PMID 28423360, 2017). "A recent study with 240 high-risk neuroblastoma patients did not identify any mutations in TIAM1 gene." (PMID 28423360, 2017). "In contrast, Tiam1 was immunoprecipitated by all three MAP1B constructs (FL, HC and LC1) in neuroblastoma cells." (PMID 23300879, 2012). "Under these conditions, endogeneous Tiam1 immunoprecipitated LC1 from neuroblastoma cells, but failed to recover the heavy chain." (PMID 23300879, 2012). "However, the oncogenic role of TIAM1 in neuroblastoma is still not clear." (PMID 28423360, 2017).